PROK1 (prokineticin 1)
Diseases named in the same sentence as PROK1 in open-access papers (continued):
Sharing a sentence is not in itself a finding about the gene and the disease.
PROK1 also shares sentences with these, for which no sentence is quoted: pancreatic duct cancer (4 papers); ovarian carcinoma (3); gastric cancer (2); gestational trophoblastic diseases (2); thyroid cancer (2); Adrenocortical Tumors (1); cervical carcinoma (1); gestational diabetes (1); Hyperinsulinemia (1); hypothyroidism (1); influenza (1); Insulin resistance (1); Lymph node metastasis (1); meningioma (1); metastasis (1); pregnancy (1).